MFN2 (mitofusin 2)
Diseases named in the same sentence as MFN2 in open-access papers (continued):
Sharing a sentence is not in itself a finding about the gene and the disease.
cancer (continued). "Although MFN2 has not been proven to act as a tumor suppressor gene in cancer cells, its antitumor function, as revealed in various tumors, continues to be accepted." (PMID 27389277, 2016). "However, our findings in the cancer cell lines did not indicate a significant upregulation of Mfn2 in ZEB1high cell lines." (PMID 40830586, 2025). "Therefore, with the exception of mitofusin-2 and PACS-2, most MAM tethering regulators show no clear association with the progression of cancer or no logical connection of their expression pattern to their role as MAM tethers." (PMID 28603693, 2017). "Noteworthy, enhanced mitochondrial fission in PDAC could be reversed by overexpression of Mfn2 or by its pharmacologic reactivation with leflunomide, an oral FDA-approved anti-arthritis drug which could be likely repurposed as chemotherapeutic agent in this cancer." (PMID 36827549, 2023).
tumor (86 papers, 2013 to 2026). "Many data indicated that MFN2 alterations are associated with mitochondrial dysfunction, which can influence tumor onset and progression." (PMID 41226512, 2025). "In human breast cancer xenografts, MFN2 downregulation promotes tumor survival and is correlated with an increased risk of cancer-related mortality." (PMID 35269393, 2022). "A recent study reported a decrease of Mfn2 mRNA levels in BC compared to normal tissues and an association between low Mfn2 expression levels and high tumor grade, stage, lymph node involvement, and shorter overall survival." (PMID 34441434, 2021). "Increased fission linked to deregulated expression of Drp1 (increased) and Mfn2 (decreased) has been observed in tumor cells but to what extent this contributes to the Warburg effect or other aspects of tumor growth remains to be determined." (PMID 24350057, 2013). "It has been shown that mitochondrial fission enhancement mediated by upregulation of DRP1 and mitochondrial fusion attenuation mediated by downregulation of MFN2 are associated with multiple cancers and promote tumor cell metastasis and drug tolerance, thus tumor progression." (PMID 37602332, 2023). "Furthermore, proteins associated with mitochondrial fusion, such as Mfn1/Mfn2 and Opa1, have been recently reported as essential players for tumor angiogenesis as they increase the oxygen consumption and cellular ATP production in liver cancer cells." (PMID 36827549, 2023). "Overexpressing Mfn2, which generally triggers mitochondrial fusion, is associated with decreased tumor development and enhanced survival in preclinical models, underscoring the connection between abnormally fused mitochondria and mitophagy-mediated tumor suppression." (PMID 38067169, 2023). "Some other potential molecules besides MFN2 may benefit both tumor therapy and tumor-associated cardiac dysfunction." (PMID 35154486, 2022). "In addition, Mfn2 expression is decreased in several tumors, whereas increased Mfn2 expression has been linked to tumor suppression." (PMID 34947882, 2021). "On the other hand, Parkin is overexpressed in melanoma compared with normal dermatic tissues, and increased Parkin levels induce metastasis and tumor growth, and the loss of Parkin suppresses tumor formation and metastasis through the inhibition of MFN2 ubiquitination." (PMID 33375363, 2020). "Notably, the increased viability of cells expressing lower amounts of MFN2 was associated to an increased, pro-survival mTORC2/Akt signaling, whose pharmacological inhibition suppresses MFN2-deficient tumor growth." (PMID 29491355, 2018). "Overall, increasing evidence suggests that a fragmented mitochondrial network, frequently associated to reduced MFN2 levels, provide tumor cells with an advantage for their growth, though the precise reasons are unknown." (PMID 29491355, 2018). "Inhibition of mTORC2 significantly suppresses MFN2 deficient tumor growth." (PMID 28176801, 2017). "The association between Mfn2 and vascular permeability may thus represent promising therapeutic targets, to reduce the influx of inflammatory cells as well as to reduce tumor metastasis or tumor growth." (PMID 33980844, 2021). "Therefore, we suspect that the regulation of Mfn2 by cordycepin is indirect, and the high mutation background of tumor cells may somehow change this regulatory relationship." (PMID 34744731, 2021). "A combination of molecular assays and single-cell transcriptomic reanalysis was employed to elucidate how MFN2 influences tumor immune escape." (PMID 41896539, 2026). "Loss of MFN2 enhanced PD-L1 expression, impaired CD8+ T-cell cytotoxicity, and accelerated tumor growth in immunocompetent mice." (PMID 41896539, 2026). "Although Mitofusin-2 (MFN2) is recognized for its role in tumor suppression, its specific contribution to the regulation of immune escape remains poorly understood." (PMID 41896539, 2026).
tumor (continued). "Our findings identify MFN2 as a critical suppressor of tumor immune evasion through the EGFR/STAT3-PD-L1 signaling pathway." (PMID 41896539, 2026). "Lastly, MFN2 can act as either a tumor suppressor or an oncogene in cancer progression, depending on the context." (PMID 41146909, 2025). "Conversely, mitochondrial fusion proteins MFN1, MFN2, and OPA1 have also been associated with tumor progression." (PMID 41146909, 2025). "During the processes of mitochondrial fission and fusion, proteins such as DRP1, MFN1, and MFN2 act to enhance the effectiveness of chemotherapy by inhibiting the metabolic pathways and proliferation of tumor cells." (PMID 39763669, 2024). "Known primarily for its role in mitochondrial dynamics and homeostasis, MFN2 also exhibits intriguing oncogenic or tumor-suppressing activities, depending on the cellular context." (PMID 39430741, 2024). "Compared with MFN1 and MFN2, which were slightly elevated in tumor spheres, the transcriptome of OPA1 was dramatically increased in CSCs." (PMID 36809297, 2023). "Overexpression of Mfn-2, inhibition of Drp-1, or knockdown of Drp-1 can reduce the proliferation of cancer cells and induce increased apoptosis of tumor cells, thereby shrinking tumors in lung, breast, and colon cancer." (PMID 37602332, 2023). "MFN2 plays diverse roles in tumor formation and progression, particularly via its effects on intracellular Ca2+ signaling, mitophagy, metabolism, the cell cycle, and apoptosis." (PMID 36877954, 2023). "Mitochondrial fusion through Drp1 depletion or MFN2 overexpression shows a tumor suppressing phenotype, which is mediated by enhanced mitophagy." (PMID 36831455, 2023). "Assessment of gene expression showed altered levels of markers of mitochondrial biogenesis and homeostasis in the tumor hosts, although only Mitofusin-2 levels were significantly affected by the treatment." (PMID 35392166, 2022). "The tumor volume in the MFN2-overexpressing Cal62 group was significantly lower than that in the control vector Cal62 group (p < 0.05)." (PMID 33479369, 2021). "In pancreatic cancer cells, leflunomide activates Mfn2, and through inhibition of de novo pyrimidine synthesis, prevents tumor cell growth and enhances the chemosensitivity of gemcitabine." (PMID 34868997, 2021). "Concordantly, the incidence of cervical LN metastases was significantly lower in the high MFN2 tumor group compare to low MFN2 tumor group (p < 0.05)." (PMID 33479369, 2021). "MFN2 (mitofusin 2) is a novel controller of mitophagy activation, which is an essential housekeeping process required to maintain tumor homeostasis." (PMID 34956177, 2021). "Through analysis, we found that the high expression of circ-MFN2 was associated with TNM stage, lymph node metastasis and tumor size." (PMID 34093664, 2021). "The expression of MFN2 was significantly decreased in tumor tissues compared with that in normal controls." (PMID 33479369, 2021). "Tumor xenograft model was constructed to evaluate the effect of circ-MFN2 knockdown on CRC tumor growth." (PMID 34093664, 2021). "The expressions of Ras, Erk1/2, Myc, mTOR and NF-κB p65 protein in tumor tissues of 2 groups were detected by Western blot, and these were decreased by treated with Adv-mfn2 comparing with the Adv-control group." (PMID 31384172, 2019). "In xenografted mouse model, we measured the tumor size before and after the Adv-mfn2 or Adv-control treatment, and analyzed the expression of Cyclin D1, Ras, Myc, ERK1/2, NF-κB p65, mTOR proteins by western blot." (PMID 31384172, 2019). "These tumor-bearing mice were treated with Adv-mfn2 or Adv-control as described in the Materials and Methods section." (PMID 31384172, 2019). "Then, Western blot was performed to confirm that Mfn2 was over expression in the tumor tissue of Adv-mfn2 group, and the expression of Cyclin D1 was decreased in Adv-control group." (PMID 31384172, 2019).
tumor (continued). "Conversely, the level of mitofusion 2 (Mfn2), which promotes mitochondrial clustering and fusion, was increased in resistant tumor cells." (PMID 29423106, 2018). "In CA4P-treated resistant tumor cells, the level of mitochondrial structural protein Tom40 was not affected, the level of Drp1 was reduced, and the level of Mfn2 was increased." (PMID 29423106, 2018). "MFN2 deficient tumor cells from both MCF-7 and A549 exhibited significant stronger progression, as evaluated by larger tumor volume over the treatment period." (PMID 28176801, 2017). "The upregulation of mitofusin-2 via inhibiting miR-761 decreased tumor growth and metastasis both in vivo and in vitro." (PMID 28603693, 2017). "Examples for such proteins are mitofusin-2 and phosphofurin acidic cluster sorting protein 2 that likely act as tumor suppressors." (PMID 28603693, 2017). "We next evaluated the tumor characterization by inhibition of mTORC2 from MFN2 knockout MCF-7 and A549 cells in vivo." (PMID 28176801, 2017). "Tumor volume and tumor weight were significantly decreased from in MFN2 knockout MCF-7 and A549 cells with administration of P529 through inhibition of cell cycle and Akt pathway." (PMID 28176801, 2017). "In summary, our in vitro and in vivo studies have demonstrated the MFN2-knockout MCF-7 and A549 cells have profound pathogenic effects on tumor progression." (PMID 28176801, 2017). "Taken together, all these results suggest that MFN2 negatively regulates tumor growth and progression." (PMID 28176801, 2017). "For cytokine–cytokine receptor interaction and focal adhesion, it makes MFN2 possible to regulate such membrane receptors result in tumor cell migration and invasion which will bring us new sight about how MFN2 inhibits tumor cell metastasis." (PMID 27389277, 2016). "Mitofusin 2 was first recognized as a key protein not only regulating mitochondria fusion but also participating in tumor cell proliferation." (PMID 27389277, 2016). "MFN2 was significantly (p < 0.0001) downregulated in tumor tissue compared with non-tumor tissue, with average mRNA expression levels of 6.76 ± 8.04 and 4.34 ± 6.06, respectively." (PMID 27389277, 2016). "Previously, we proved that overexpression of the MFN2 gene in HCC resulted in tumor cell apoptosis via mitochondrial pathways mediated by calcium influx." (PMID 27389277, 2016). "The MFN2 mRNA expression was higher in 76.5 % of the non-tumor hepatic tissues than in the paired HCC tissue." (PMID 27389277, 2016). "We confirmed that Mfn2 expression was lower in tumor tissue than in normal gastric mucosal tissue and that it was negatively correlated with tumor size, indicating an anti-tumor role for Mfn2." (PMID 23797661, 2013). "Notably, the upregulation of MFN2 can be achieved through the miR-761, and then disrupts mitochondrial function and significantly inhibits tumor growth and metastasis in both in vivo and in vitro." (PMID 40661148, 2025). "MFN2 has anti-tumor effects and is downregulated in multiple cancers." (PMID 38637555, 2024). "Similarly, Leflunomide, an FDA-approved arthritis drug, was shown to increase Mfn2 expression and suppress tumor growth in a study of pancreatic ductal adenocarcinoma, indicating its potential repurposed used as a chemotherapeutic agent." (PMID 38489056, 2024). "On the other hand, Ca2+ acts as an important regulator of cell migration, and the effect of MFN2 on Ca2+ flux may also be closely related to tumor metastasis." (PMID 36877954, 2023). "MFN2-mediated mitochondrial fusion shows tumor suppressing phenotypes." (PMID 36831455, 2023). "Parkin can directly bind and ubiquitinate MFN2, promoting melanoma tumor formation and metastasis." (PMID 35269393, 2022). "Thus, we manipulated DRP1 fission and MFN2 fusion activities to disintegrate mitochondrial hyperfusion and promote selective mitophagy that ultimately leads to the disruption of tumor cell adaptation to extracellular acidosis." (PMID 35410237, 2022).
tumor (continued). "In addition to this observation, other authors demonstrated that the expression of MFN2 was significantly decreased in tumor tissues." (PMID 35565283, 2022). "Studies have found that key molecules involved in the regulation of mitochondrial fission and fusion, such as Drp1, MFN1, and MFN2, are abnormally expressed in a variety of tumor tissues, and may be closely related to tumor progression." (PMID 36034426, 2022). "Mitofusin-2 (MFN2), a member of the mitochondrial fusion protein family located in the outer mitochondrial membrane, has already been reported to possess anti-tumor potential via various mechanisms, such as inducing apoptosis and promoting promoter DNA hypermethylation 13-16." (PMID 35154486, 2022). "Furthermore, some studies have reported that MFN2 exerts anti-tumor effects; in our study, we also confirmed that MFN2 promoted RIP3/MLKL complex-induced necroptosis in the Huh7 cell line." (PMID 35154486, 2022). "Interestingly, tumor MFN2 mRNA expression was found to significantly correlate with gender and preoperative alpha-fetoprotein levels." (PMID 34073868, 2021). "On the other hand, this study pointed out that Mfn2 silencing in BC cells promoted proliferation, migration, and invasion in vitro models and enhanced tumor progression in vivo suggesting that BC progression may be delayed by increasing Mfn2 expression." (PMID 34441434, 2021). "Thus, miR-761 is upregulated in HCC, and an inhibitor of miR-761 upregulates MFN2, which suppresses tumor growth and metastasis both in vivo and in vitro." (PMID 34073868, 2021). "MFN2 might play a role as a tumor suppressor on both proliferation and cell invasion in the other cancers." (PMID 33479369, 2021). "MFN2 might involve in cell cycle regulation, apoptosis, and differentiation, and it might play a role as a tumor suppressor in carcinogenesis." (PMID 33479369, 2021). "Then, the in vivo experiment also confirmed that Mfn2 could inhibit the tumor growth, and depress the Cyclin D1, Ras, Myc, NF-κB p65, Erk1/2 and mTOR protein expression." (PMID 31384172, 2019). "As a tumor suppressor gene, Mfn2 plays large roles in managing cell proliferation and apoptosis." (PMID 30410558, 2018). "In recent years, Mfn2 has also shed new light on the area of tumor research." (PMID 30046371, 2018). "Given that the invasive property of tumor cells contributes to poor prognosis, we next addressed whether MFN2 affects cell migration and invasion." (PMID 28176801, 2017). "A role in ER–mitochondria contact formation raises the possibility that mitofusin-2 could also play a role as an oncoprotein or tumor suppressor." (PMID 28603693, 2017). "We next examined the impact of MFN2 knockout on tumor growth in vivo." (PMID 28176801, 2017). "There is accumulating evidence that MFN2 influences tumor growth and progression, however, the mechanism(s) by which this occurs remains unclear." (PMID 28176801, 2017). "A special vehicle carrying the human Mfn2 gene may be injected into specific organs, and stably inhibit tumor growth and metastasis in the long term." (PMID 25120590, 2014). "We further investigated whether overexpression of MFN2 affected sor-induced anti-tumor effects." (PMID 35154486, 2022). "Furthermore, due to the lack of clinical studies with MFN2 intervention in various patient cohorts, whether MFN2 can benefit tumor patients with cardiac complications still needs further study." (PMID 35154486, 2022). "It is worth noting that MFN2 was initially referred to as a hyperplasia suppressor gene when it was cloned because of its anti-proliferative effect, and has been reported to regulate cell proliferation and the apoptosis of multiple tumor cell lines and vascular smooth muscle cells." (PMID 35453623, 2022). "Moreover, most of the studies on the role of MFN2 in autophagy have been performed in tumor cells where autophagy has a dual significance in response to diverse nutrient conditions, possibly acting as either a tumor-suppressor or -promoting pathway." (PMID 40396043, 2022).